ENSG00000301113 (novel transcript)
Gene: Long non-coding RNA gene on chromosome 10 (29,367,254 to 29,369,135, forward strand). Ensembl gene ENSG00000301113.
Gene Ontology:
Biological process: SRP-dependent cotranslational protein targeting to membrane, signal sequence recognition
Cellular component: signal recognition particle, endoplasmic reticulum targeting